DEFB112 (defensin beta 112)
Description:
Has antibacterial activity.
Synonyms: DEFB-12
Gene: Protein-coding gene on chromosome 6 (50,042,099 to 50,049,929, reverse strand). Ensembl gene ENSG00000180872.
Subcellular location: Secreted
Pathways (Reactome):
Immune System: Beta defensins; Defensins
Genetic constraint (gnomAD): Loss-of-function variants: 6 observed, 3.17 expected, observed/expected ratio (o/e) 1.89, 90% interval 0.87 to 1.96. That is too few expected variants to judge how well the gene tolerates losing a copy. Missense variants: 120 observed, 99.74 expected, observed/expected ratio (o/e) 1.2, 90% interval 1.04 to 1.4. Synonymous variants: 40 observed, 32.96 expected, observed/expected ratio (o/e) 1.21, 90% interval 0.94 to 1.58.
Homologues: Orthologues: chimpanzee DEFB112 (83% identical), macaque DEFB112 (77% identical), dog DEFB112 (31% identical).
Diseases named in the same sentence as DEFB112 in open-access papers:
DEFB112 is named in the same sentence as 2 diseases in open-access papers, as found by Europe PMC text mining. Sharing a sentence is not in itself a finding about the gene and the disease.
DEFB112 shares sentences with these, for which no sentence is quoted: metastatic melanoma (1 paper); metastatic tumors (1).